P2RX5-TAX1BP3 (P2RX5-TAX1BP3 readthrough (NMD candidate))
Gene: Protein-coding gene on chromosome 17 (3,663,063 to 3,696,194, reverse strand). Ensembl gene ENSG00000257950.
Genetic constraint (gnomAD): Missense variants: 529 observed, 528.77 expected, observed/expected ratio (o/e) 1, 90% interval 0.93 to 1.08. Synonymous variants: 215 observed, 221.23 expected, observed/expected ratio (o/e) 0.97, 90% interval 0.87 to 1.09.